GTF2A2 (general transcription factor IIA subunit 2)
Description:
TFIIA is a component of the transcription machinery of RNA polymerase II and plays an important role in transcriptional activation. TFIIA in a complex with TBP mediates transcriptional activity.
Synonyms: TFIIA-12; TFIIAS; TFIIA-gamma; TF2A2; TFIIA; HsT18745; T18745
Tractability: Small molecule: a structure with a bound ligand is known. PROTAC: ubiquitination databases record sites on it; its protein half-life has been measured.
Gene: Protein-coding gene on chromosome 15 (59,638,058 to 59,657,541, reverse strand). Ensembl gene ENSG00000140307.
Subcellular location: Nucleus
Subcellular location (Human Protein Atlas): Nucleoplasm
Pathways (Reactome):
Gene expression (Transcription): RNA Polymerase II Pre-transcription Events; RNA Polymerase II Promoter Escape; RNA Polymerase II Transcription Initiation; RNA Polymerase II Transcription Initiation And Promoter Clearance; RNA Polymerase II Transcription Pre-Initiation And Promoter Opening; RNA polymerase II transcribes snRNA genes
Disease: HIV Transcription Initiation; RNA Polymerase II HIV Promoter Escape; Transcription of the HIV genome
Signal Transduction: Estrogen-dependent gene expression
Gene Ontology:
Molecular function: protein binding; protein heterodimerization activity; protein homodimerization activity; RNA polymerase II general transcription initiation factor activity; RNA polymerase II general transcription initiation factor binding; TBP-class protein binding; RNA polymerase II-specific DNA-binding transcription factor binding
Biological process: positive regulation of transcription by RNA polymerase II; positive regulation of transcription initiation by RNA polymerase II; RNA polymerase II preinitiation complex assembly; transcription by RNA polymerase II; transcription initiation at RNA polymerase II promoter
Cellular component: nucleoplasm; nucleus; transcription factor TFIIA complex; transcription factor TFIID complex
Homologues: Orthologues: chimpanzee GTF2A2 (100% identical), guinea pig GTF2A2 (99% identical), macaque GTF2A2 (99% identical), mouse Gtf2a2 (99% identical), pig GTF2A2 (99% identical), rabbit GTF2A2 (99% identical), zebrafish gtf2a2 (94% identical), tropical clawed frog gtf2a2 (90% identical), Drosophila melanogaster TfIIA-S (74% identical), Drosophila melanogaster TfIIA-S-2 (48% identical), Caenorhabditis elegans gtf-2A2 (47% identical), Caenorhabditis elegans B0336.13 (41% identical).
Diseases named in the same sentence as GTF2A2 in open-access papers:
GTF2A2 is named in the same sentence as 6 diseases in open-access papers, as found by Europe PMC text mining. Sharing a sentence is not in itself a finding about the gene and the disease. The quoted sentences say what the papers report.
leukemia (2 papers, 2021). A malignant (clonal) hematologic disorder, involving hematopoietic stem cells and characterized by the presence of primitive or atypical myeloid or lymphoid cells in the bone marrow and the blood. "In addition, we identified genes of previously unknown cancer relevance with regards to leukemia circulation (e.g., LRIF1, DNAJC1, and CMC2) and therapeutic treatment (e.g., EBPL, MESDC2, ZRANB2, GTF2A2)." (PMID 34764253, 2021).
systemic lupus erythematosus (1 paper, 2023). An autoimmune multi-organ disease typically associated with vasculopathy and autoantibody production. "Although the role of GTF2A2 in RA is currently unknown, it has been previously found in systemic lupus erythematosus (SLE) that point mutations in the expression quantitative trait loci (eQTL) of this transcription factor subunit are associated with type I interferon levels." (PMID 37005480, 2023).
cancer (3 papers, 2013 to 2023). A tumor composed of atypical neoplastic, often pleomorphic cells that invade other tissues. "Both GTF2A2 and GTF2E2 are known to be involved in the initiation of RNA transcription and are frequently overexpressed in cancer." (PMID 37631095, 2023).
infection (1 paper, 2015). The state of being infected such as from the introduction of a foreign agent such as serum, vaccine, antigenic substance or organism. "Another protein coding gene similar to this pseudogene, GTF2A2, is found downregulated in uninfected T-cells in response to exposure to the HIV-1 gp120/V3 epitope, similar to our observation at 24 h post-infection." (PMID 26426037, 2015).
GTF2A2 also shares sentences with these, for which no sentence is quoted: endometrioid endometrial adenocarcinoma (1 paper); tumor (1).